IGDCC3 (immunoglobulin superfamily DCC subclass member 3)
Synonyms: PUNC; HsT18880
Tractability: Antibody: UniProt predicts a signal peptide or a membrane-spanning region.
Gene: Protein-coding gene on chromosome 15 (65,327,127 to 65,378,078, reverse strand). Ensembl gene ENSG00000174498.
Subcellular location: Membrane
Subcellular location (Human Protein Atlas): Nucleoplasm; Vesicles
Gene Ontology:
Molecular function: protein binding
Biological process: cell-cell adhesion
Cellular component: membrane
Genetic constraint (gnomAD): Loss-of-function variants: 49 observed, 72.64 expected, observed/expected ratio (o/e) 0.67, 90% interval 0.54 to 0.86. The upper end of that interval is the gene's LOEUF score, 0.86, which puts it in group 3 of 6, group 1 being the genes least tolerant of losing a copy. Missense variants: 1,038 observed, 1,090.5 expected, observed/expected ratio (o/e) 0.95, 90% interval 0.9 to 1. Synonymous variants: 477 observed, 463.3 expected, observed/expected ratio (o/e) 1.03, 90% interval 0.95 to 1.11.
Homologues: Orthologues: chimpanzee IGDCC3 (99% identical), macaque IGDCC3 (97% identical), pig IGDCC3 (88% identical), dog IGDCC3 (87% identical), mouse Igdcc3 (86% identical), rat Igdcc3 (84% identical), guinea pig IGDCC3 (81% identical), rabbit IGDCC3 (81% identical), tropical clawed frog IGDCC3 (57% identical), zebrafish igdcc3 (57% identical). Paralogues in human: IGDCC4 (37% identical), PRTG (35% identical), ROBO1 (24% identical), ROBO2 (23% identical), SDK2 (23% identical), SDK1 (22% identical), DCC (22% identical), ROBO3 (22% identical), NEO1 (21% identical), MXRA5 (21% identical), CDON (20% identical), BOC (20% identical), and 24 more.
Diseases named in the same sentence as IGDCC3 in open-access papers:
IGDCC3 is named in the same sentence as 4 diseases in open-access papers, as found by Europe PMC text mining. Sharing a sentence is not in itself a finding about the gene and the disease. The quoted sentences say what the papers report.
breast carcinoma (1 paper, 2020). "IGDCC3 is also potential prognostic marker that is associated with overall survival (OS) and risk of recurrence in breast cancer." (PMID 33473258, 2020).
cholangiocarcinoma (1 paper, 2023). A carcinoma that arises from the intrahepatic biliary tree (intrahepatic cholangiocarcinoma) or from the junction, or adjacent to the junction, of the right and left hepatic ducts (hilar cholangiocarcinoma). "TH, IGDCC3, RAD51AP2, and MUC2 are genes that were identified by WGCNA and are related to the clinical prognosis and survival of cholangiocarcinoma, but they have already been reported." (PMID 36979826, 2023).
sarcoma (1 paper, 2020). A usually aggressive malignant neoplasm of the soft tissue or bone. "By analyzing the results of the drug‐gene interaction network and DEG analysis results, we found that rilmenidine can exert a drug effect in sarcomas by interacting with the immunoglobulin superfamily DCC subclass member 3 (IGDCC3) gene." (PMID 32780509, 2020).
tumor (1 paper, 2023). "Furthermore, we identified eight hub genes (VSNL1, TH, PCP4, IGDCC3, RAD51AP2, MUC2, BUB1, and BUB1B) that promoted tumor progression and were associated with prognosis according to the Kaplan–Meier and ROC curve analyses." (PMID 36979826, 2023).